HMGB1 (high mobility group box 1)
Diseases named in the same sentence as HMGB1 in open-access papers (continued):
Sharing a sentence is not in itself a finding about the gene and the disease.
tumor (continued). "Moreover, it has been shown that HMGB1-deficient tumors resist DNA-alkylating therapies and have an impaired ability to recruit immune cells into the treated tumor tissue, resulting in impaired apoptosis and improved cancer cell survival." (PMID 40804938, 2025). "First, OVs selectively infect and lyse tumor cells, inducing immunogenic cell death (ICD) and releasing damage-associated molecular patterns (DAMPs), including ATP, HMGB1, and calreticulin, alongside tumor-associated antigens (TAAs), thereby mediating direct tumor cytotoxicity." (PMID 41451200, 2025). "Multivariate logistic regression analysis identified tumor diameter, Ki67, molecular subtype, number of metastatic sites per patient, and HMGB1 were independent risk factors for poor prognosis in MBC patients, whereas caspase‐1 was an independent protective factor against poor prognosis." (PMID 41479846, 2025). "Radiation can cause immunogenic death of tumor cells by inducing the release of HMGB1." (PMID 40356601, 2025). "The ranking list of tumors according to their rate of HMGB1 deficiency provides probably the most comprehensive view of this alteration available to date, although the accuracy of our data is still limited by small numbers in some tumor categories." (PMID 40804938, 2025). "The immunological mechanisms underlying this phenomenon have been gradually uncovered: radiotherapy induces immunogenic cell death, releasing signals such as tumor-associated antigens, damage-associated molecular patterns, and high mobility group box 1 (HMGB1)." (PMID 41567624, 2025). "In addition, the extensive tumor cell death caused by anti-tumor drugs leads to the release of various danger-associated molecular patterns (DAMPs), many of which act as immunosuppressive mediators, such as HMGB1 and IL-33." (PMID 39994810, 2025). "Moreover, ferroptosis-associated danger signals such as HMGB1 can reinforce this pro-tumor state by promoting M2 macrophage polarization, establishing a self-perpetuating feedback loop." (PMID 41293165, 2025). "TMZ-induced HMGB1 secretion facilitates M1-like polarization of tumor-associated macrophages (TAMs) through the receptor for advanced glycation end-products (RAGE)/extracellular signal-regulated kinase (ERK)/inhibitor of kappa B (IκB)/nuclear factor kappa B (NF-κB) signaling pathway." (PMID 39893499, 2025). "Additionally, HMGB1 promotes the formation of a tumor-supportive microenvironment by activating survival-related signaling pathways and recruiting tumor-associated macrophages, further compromising the effectiveness of radiotherapy." (PMID 40969278, 2025). "High HMGB1 expression was associated with unfavourable tumour characteristics and shorter survival." (PMID 38353760, 2024). "HMGB1 can promote the presentation of tumor‐associated antigens to APCs." (PMID 38911063, 2024). "Similarly, high-HMGB1 expression was associated with larger (> 3 cm) tumours, lymphatic invasion and lymph node metastases." (PMID 38353760, 2024). "Moreover, the tumor-specific cytoplasmic expression of HMGB1 is further linked to immunological tolerance and poor clinical outcomes." (PMID 38725632, 2024). "HMGB1 also induced the ability of PBMC to cause tumor cell death." (PMID 38203798, 2024). "Interestingly, high expression of HMGB1 is closely associated with immune evasion mechanisms in cancer, particularly in tumor-associated macrophages." (PMID 39507236, 2024). "Moreover, HMGB1-positive TANs were recruited to tumor lesions and closely associated with the pathological grades of primary tumors, facilitating immune evasion via the GATA2/HMGB1/TIM-3 axis." (PMID 38877579, 2024). "ATP initiates the recruitment of APCs in the tumor bed, CRT facilitates the phagocytosis of dead cells, HMGB1 promotes the presentation of numerous tumor-associated antigens (TAAs) to APCs, and HSPs mediate the maturation and migration of dendritic cells (DCs)." (PMID 38803535, 2024).
tumor (continued). "Also increased cytoplasmic HMGB1 was significantly associated with smaller tumor size, earlier stages, luminal subtype, and hormone receptor expression." (PMID 39830522, 2024). "Previous researches have indicated that ICD can induce adaptive immune response against the antigens of dead or dying tumor cells through damage-associated molecular patterns (DAMPs), which include ATP release, calreticulin exposure, and HMGB1 (high mobility group box 1) secretion." (PMID 37662929, 2023). "Studies suggest that HMGB1 is closely associated with tumor proliferation." (PMID 37291495, 2023). "Moreover, HMGB1 released into the extracellular environment infiltrates into the surrounding brain tissue to proliferate the surrounding tumor cells, causing the regeneration of small blood vessels to promote spreading and tumor growth." (PMID 37210579, 2023). "The receptor for advanced glycation endproducts (RAGE) and its two dominant ligands S100A8/A9 and high mobility group box protein 1 (HMGB1) have been implicated as regulatory elements promoting tumor progression in hundreds of studies in both human and mouse systems." (PMID 36831371, 2023). "HMGB1, a nuclear protein that intervenes in the communication between tumor cells and the immune system, is a damage-associated molecule (DAMP) that is released during stress or hypoxia and acts as an alarmin or a cytokine able to relay signals of danger to immune cells." (PMID 36769076, 2023). "Therefore, while epithelial HMGB1 doesn’t directly impact survival, strong cytoplasmic HMGB1 expression is associated with an ‘immune cold’ tumour microenvironment which we have demonstrated confers a poor prognosis in CRC." (PMID 36980751, 2023). "However, radiotherapy causes tumor cell death and the release of HMGB1, and the extracellular HMGB1 has the potential to enhance tumor progression." (PMID 36831371, 2023). "Oncolytic viral therapy relies on tumor cell destruction, which has been shown by multiple labs to result in the release of damage-associated molecular patterns (DAMPs) such as ATP, calreticulin, and HMGB1." (PMID 36789106, 2023). "More importantly, Ca2+ released from CaP had the ability to cause the ectopic release of CRT to the cell surface and HMGB1 expression, promoting the uptake, processing, and presentation of tumor antigens by DCs and leading to the recruitment and infiltration of T cells." (PMID 37933288, 2023). "RT-injured tumor and tumor-infiltrating cells release intracellular molecules known as damage-associated molecular patterns (DAMPs), or alarmins, including high-mobility group box 1 (HMGB1), ATP, and calreticulin." (PMID 36831435, 2023). "One of the initial steps following tumor cell damage is the enhanced release of damage-associated molecules, such as calreticulin, adenosine triphosphate (ATP), GM-CSF, high-mobility group box 1 (HMGB1), and heat shock proteins (HSPs)." (PMID 36139368, 2022). "In addition, the positive correlations were detected between HMGB1 expression and the immune infiltration of cancer‐associated fibroblasts in the TCGA tumours of BRCA‐LumA, MESO and TGCT based on all or most algorithms." (PMID 35765707, 2022). "Simultaneously, the dying tumor cells undergo organellar and cellular stress and can secrete damage-associated molecular patterns (DAMPs), including calreticulin, adenosine triphosphate (ATP) and high-mobility group box 1 (HMGB1)." (PMID 35959371, 2022). "Additionally, even though numerous xenografts or transplantable tumor models have been employed, generating HMGB1-associated spontaneous tumor models is crucial." (PMID 36428714, 2022). "TDEs also engage with other TLRs such as TLR4 and TLR7 on other phagocytes including monocytes and neutrophils in which miRNA, noncoding RNA, and high-mobility group box 1 (HMGB1) transferred by TDEs are implicated in driving the pro-tumor phenotype of these myeloid cells." (PMID 36031601, 2022).
tumor (continued). "Physical characteristics of the tumor environment such as hypoxia can cause tumor cell death, potentially resulting in the release of DAMPs such as Heat shock proteins (HSPs) and high mobility group box 1 (HMGB1), which act as ligands for Toll-like receptors on innate immune cells." (PMID 36612080, 2022). "TMZ treatment caused HMGB1 release from GBM cells in tumor tissue of patients." (PMID 36686729, 2022). "Interestingly, yet another receptor of HMGB1, TIM‐3, expressed at the surface of tumour‐associated DCs, was recently shown to compete with nucleic acids for binding to HMGB1, thereby dampening the efficacy of antitumour DNA vaccines or chemotherapy." (PMID 35344301, 2022). "When tumor cells die, many of them go through cell necrosis and release damage-associated molecular pattern molecules (DAMPs), such as high mobility group box-1 (HMGB1)." (PMID 36294824, 2022). "Furthermore, the immune checkpoint receptor T-cell immunoglobulin and mucin-domain containing-3 (TIM-3) on tumor-associated DCs was able to abrogate therapy-induced immunogenicity of cell death by interacting with HMGB1." (PMID 34025657, 2021). "The interaction of TIM-3 specifically expressed on tumor-associated dendritic cells (TADCs) and the nuclear protein high mobility group box 1 (HMGB1) could inhibit the activation of nucleic acid-mediated anti-tumor immune responses." (PMID 34743730, 2021). "Necrotic tumor cells release their intracellular components, some of which act as functional inflammatory mediators, the so-called damage-associated molecular patterns (DAMPs), such as IL-1α, ATP, and high mobility group box 1 (HMGB1)." (PMID 34063828, 2021). "HMGB1 encodes a protein that belongs to the high mobility group-box superfamily and plays an important role in several cellular processes, including inflammation, cell differentiation, and tumor cell migration." (PMID 34336950, 2021). "Targeting HMGB1 (Glycyrrhizin) could remarkably suppress ESCC tumor growth in vitro and in vivo, especially in KDM4D-deficient cells." (PMID 34820329, 2021). "In tumor cells, this HMGB1–RAGE interaction may be associated with the development of cisplatin resistance." (PMID 34966671, 2021). "During immunogenic cell death, radiation-damaged tumor cells subsequently activate APCs by translocating or releasing endogenous damage-associated molecular patterns (DAMPs) such as, calreticulin, ATP, and high-mobility-group-box-1 (HMGB1) that activates TLR4." (PMID 34497773, 2021). "Moreover, we provide the in vivo evidence that the deficiency of HMGB1 reduces cisplatin-resistant tumor growth." (PMID 34094941, 2021). "Elevated HMGB1 is associated with malignant phenotypes, including tumor invasion and metastasis." (PMID 34867338, 2021). "Comparatively the amount of HMGB1 secreted in apoptosis is lower than it is in necrosis, however, the response caused by macrophages in the absorption of dead tumor cells, again induces an active release of HMGB1, with the consequent accumulation of this protein in TME." (PMID 34198850, 2021). "To confirm whether tumor heterogeneity evaluated by TA was associated with HMGB1 expression, we compared parameters from TA according to HMGB1 expression." (PMID 34244567, 2021). "Aside, it is worth mentioning that in a separate study, treatment-induced pyroptosis in melanoma cells via GSDME and caspase-3 accordingly promoted HMGB1 release and was directly tied to the infiltration of both tumor-associated T cells and activated dendritic cells." (PMID 34429144, 2021). "Moreover, treatment with PV-10 in melanoma patients resulted in increased levels of HMGB1 in the serum, which was associated with improved anti-tumor activity of circulating T cells." (PMID 34187428, 2021). "Also, HMGB1 expression was significantly associated with pathological T stage (p < 0.0001), tumor grade (p = 0.0002), LVI (p = 0.0116) and concomitant CIS (p = 0.0184)." (PMID 34244567, 2021).
tumor (continued). "Interestingly, both oxaliplatin and cisplatin induced the release of HMGB1, but it was only oxaliplatin that caused calreticulin translocation and effectively contributed towards tumor immunogenicity." (PMID 32781554, 2020). "Calreticulin serves as an “eat me” signal, ATP recruits dendritic cells to the tumor sites to cause their maturation to antigen-presenting cells, and HMGB1 facilitates the Toll-like receptor 4 dependent cross-presentation of the released tumor antigens to cytotoxic T-cells." (PMID 32781554, 2020). "It was shown that in this case, HmgB1 inhibits DNA repair after damage resulted from formation of stable DNA–cisplatin–HmgB1 complex, which might affect tumor susceptibility to chemotherapy." (PMID 33114717, 2020). "HMGB1 has been recognized to activate the immature dendritic cells and to generate tumor-specific cytotoxic T-lymphocytes against A20 lymphoma cells causing tumor cell lysis." (PMID 32575664, 2020). "Immunogenic cell death (ICD) consists of the release of damage-associated molecular patterns (DAMPs e.g., HMGB1, ATP, Type I interferons) accompanied by tumor-associated antigens (TAA) and tumor-specific antigens (TSA) that are captured and presented by antigen-presenting cells (APCs)." (PMID 33213060, 2020). "In the setting of cancer, HMGB1 is released from lysed and stressed cells into the extracellular space, causing chronic inflammation, attracting immune cells to the tumor site and engaging RAGE and Toll-like receptors to initiate and propagate inflammatory responses." (PMID 33013860, 2020). "For the entire group of 50 patients, plasma HMGB1 showed a modest variation over the neoadjuvant treatment course, which first led us to investigate whether tumor mutational KRAS status might identify cases with ICD response." (PMID 31893287, 2020). "Moreover, HMGB1 overexpression in EMT6 cells (in situ) can cause more EMT6-luciferase tumor cells (i.v.)to remain in lung tissue." (PMID 32943604, 2020). "Several mechanisms may contribute to the pathogenesis of HMGB1-associated tumor promotion, most prominent among which is an indirect mechanism linked to perpetuation of chronic inflammation of both infective and noninfective origin." (PMID 32664328, 2020). "In this context, the discovery of HMGB1 redox modulation represented a breakthrough in the field, and our findings now reveal a highly dynamic regulation of HMGB1 oxidation in vivo, both upon tissue injury and in the tumor microenvironment, which is tightly associated to inflammatory processes." (PMID 32670275, 2020). "We thus sought to determine whether the autophagy-deficient tumor tissues also release HMGB1, which might result in a positive feedback enhancement." (PMID 32382012, 2020). "This immunogenic tumor death will result in the release of various damage-associated molecular patterns (DAMPs) such as adenosine triphosphate (ATP), high-mobility group protein B1 (HMGB1), and heat-shock proteins that will recruit various antigen presenting cells." (PMID 32911646, 2020). "HMGB1 signaling, associated with inflammatory responses and tumor metastasis, was also activated." (PMID 33347497, 2020). "RT induces immunogenic cancer cell death, which results in calreticulin (CRT) exposure on the cells surface and the release of tumor neoantigens as well as death-associated molecular patterns (DAMPs; among others, adenosine triphosphate (ATP) and high mobility group box 1 (HMGB1) protein)." (PMID 32605154, 2020). "In addition, the reduced form of secreted HMGB1 promotes the processing and presentation of tumor-associated antigens by DCs, however, the fully oxidized HMGB1 is inactive and unable to promote DC activation." (PMID 33447347, 2020).
tumor (continued). "The spatiotemporal release of HSP70, calreticulin, HMGB1, and some other molecules, e.g., ATP or S100 proteins from tumor cells, are known as damage-associated molecular pattern (DAMP) signals that can promote the uptake, processing, and presentation of tumor antigens by DCs." (PMID 32872532, 2020). "To test this hypothesis, we checked the ICD hallmark: HMGB1 secretion in β-lap-treated tumor cells in vitro." (PMID 31324798, 2019). "We questioned whether the release of HMGB1 in response to radiation was associated with changes in the tumor immune landscape and more importantly whether its involvement in tumor radioresistance was immune mediated." (PMID 31015520, 2019). "Furthermore, the binding of HMGB1 to RAGE has been associated with tumor growth and metastasis in a murine model." (PMID 31779212, 2019). "Importantly, recent studies have found that HMGB1 expression is associated with tumorigenesis and tumor progression." (PMID 31399104, 2019). "Overexpression of HMGB1 in tumor is associated with poor prognosis in many cancers." (PMID 30988279, 2019). "Similarly, we reported that in an autophagy-deficiency-related hepatic tumorigenesis, HMGB1 plays a vital role in tumor formation." (PMID 31731454, 2019). "HMGB1, released from tumor cells upon chemotherapy or radiotherapy, is an important component of disordered tumor microenvironment and highly associated with cancer hallmarks including sustain proliferation, resistance to cell death, invasion and metastasis, and recurrence." (PMID 31558702, 2019). "Genetic ablation of Hmgb1 delayed the tumor development in autophagy-deficient livers." (PMID 31731454, 2019). "We examined the association of tumor HMGB1 expression with in-field recurrence after PORT which may reflect tumor radioresistance." (PMID 30755598, 2019). "In addition to TLR9-mediated tumor DNA sensing, we have previously found that TLR4 also promotes activation of tumor-specific CTLs after chemotherapy by recognizing the chromatin-associated factor HMGB1 released from dying tumor cells." (PMID 31619293, 2019). "As a consequence of ICD, damage-associated molecular patterns (DAMPs), such as ATP, uric acid and high mobility group protein Box1 (HMGB1), from tumor cells and by the translocation of calreticulin, an ER- associated chaperone, to the tumor cell surface are released and amplify immune response." (PMID 30352078, 2018). "In the mentioned study, the expression of HMGB1 was significantly associated with the clinicopathological characteristics, which is in congruence with our findings due to the difference in expression between the tumor and normal tissues." (PMID 30245980, 2018). "HMGB1 is a member of the danger associated molecular patterns (DAMPs) family that has divergent biological functions including inflammation, autophagy/apoptosis, promotes tumor cell survival, and mediates immune responses." (PMID 30643519, 2018). "This study aimed to clarify whether miR-200c acts as a tumour suppressor in NSCLC by downregulating HMGB1, which is associated with EMT, invasion, cytoskeleton rearrangement, and migration in vitro and in vivo." (PMID 28727734, 2017). "One hypothesis was that HMGB1 directly inhibited the differentiation and proliferation of T cells and B cells, and then caused tumor cell to escape from monitoring and killing by the immune system." (PMID 28968989, 2017). "The tumor associated-soluble factors such as HMGB1, growth factors, chemokines and cytokines could contribute to the tumor growth through the regulation and alteration of tumor microenvironment." (PMID 26745884, 2016). "Interestingly, however, it has been shown that cancer-associated fibroblasts that are strongly involved in tumor progression induced HMGB1 upregulation in breast cancer cells, thus contributing to resistance of the latter cells to doxorubicin." (PMID 26925422, 2016).